PDCD1 (programmed cell death 1)
Diseases named in the same sentence as PDCD1 in open-access papers (continued):
Sharing a sentence is not in itself a finding about the gene and the disease.
tumor (continued). "Moreover, DMPMs harboring 3p21 locus or BAP1 loss showed an inflammatory tumor microenvironment and expression of programmed cell death 1 (PD1)/programmed cell death 1 ligand (PD-L1), so this subset of DMPMs may be eligible for immune checkpoint blockade therapies." (PMID 31752449, 2019). "These drugs, including anti–cytotoxic T-lymphocyte antigen 4 (CTLA-4) antibodies and anti–programmed cell death-1 (anti-PD-1)/programmed cell death ligand-1 (PD-L1) antibodies, reactivate the anti-tumor immunity of T cells." (PMID 30616523, 2019). "Aside from the continued demethylation of the PDCD1 locus, dysfunctional T cells gradually undergo de novo methylation of genes involved in effector functions during persistent infections and tumor progression, limiting T cell expansion and clonal diversity." (PMID 31379886, 2019). "The programmed cell death-1 (PD-1)/ programmed cell death-ligand (PD-L) pathway acts as an immune checkpoint for tumor cells to evade host immune surveillance." (PMID 31718692, 2019). "Similar results were obtained with TRACCAR T cells engineered to express IL-12P70 under the control of PDCD1 regulatory elements, in which we also observed an increase of ΔLNGFR upon tumor cell engagement (blue square)." (PMID 31723132, 2019). "Anti- programmed cell death 1 (PD-1)/ligand 1(PD-L1) therapy is effective in multiple tumor types, and can bring remarkable clinical benefits with limited toxicity." (PMID 31527697, 2019). "TTF have been shown to lead to an aberrant mitotic exit (which can induce ICD), expose CRT on cell surface and decrease tumor volume when combined with an anti-programmed cell death 1 (anti-PD-1) drug." (PMID 30619273, 2018). "PD-L1 interacts with PD-1 (programmed cell death-1) on T cells, inhibiting T-cell proliferation and effector functions such as cytokine secretion and tumor cell-killing." (PMID 29687231, 2018). "Several anti-programmed cell death-1 (PD-1) and anti-programmed cell death ligand-1 (PD-L1) therapies have shown encouraging safety and clinical activity in a variety of tumor types." (PMID 30041679, 2018). "The second class of immune checkpoint inhibitors that are transforming standard of care across a range of tumour types are inhibitors of programmed cell death-1/programmed cell death ligand-1 (PD-1/PD-L1) signalling." (PMID 29123260, 2018). "Subsequent successes followed with antibodies against programmed cell death-1 (PD-1) and programmed death ligand-1 (PD-L1), confirming the broad utility of blocking inhibitory pathways that interfere with anti-tumor T cell responses." (PMID 30854331, 2018). "CD8+ T cells among the tumor-infiltrating lymphocytes (TILs) express significantly higher levels of immune checkpoint receptors such as programmed cell death 1 (PD-1) than those in the peripheral blood." (PMID 29368602, 2018). "Programmed cell death 1 (PD-1) and programmed cell death-ligand 1(PD-L1) inhibitors have captured our attention as new therapeutic options for several tumor types." (PMID 29545941, 2018). "Recently, tumor immunotherapies, which is focused on several immune checkpoint molecules, such as programmed cell death-1 (PD-1), programmed cell death-ligand 1 (PD-L1), and cytotoxic T-lymphocyte-associated antigen 4 (CTLA-4), have emerged." (PMID 29556567, 2018). "In a large Phase I/Ib study, Pegilodecakin achieved objective responses across multiple tumor types, alone and in combination with chemotherapies and Programmed Cell Death-1 (PD-1) inhibitors." (PMID 30400835, 2018). "The programmed cell death-ligand 1 (PD-L1) on tumor cells has an important role in avoiding host immune surveillance by interacting with the programmed cell death-1 (PD-1) on immune cells in the tumor microenvironment." (PMID 28969039, 2017). "In this context, it would be crucial to define thresholds for PDCD1 methylation and consecutive PD-1 expression on T cells that establish anti-tumor immunity." (PMID 28487502, 2017).
tumor (continued). "Checkpoint inhibitors such as nivolumab or pembrolizumab (programmed cell death 1 or PD-1 inhibitors) and ipilimumab (a cytotoxic T-lymphocyte-associated protein 4 or CTLA-4 inhibitor) enhance the immune response to a tumor." (PMID 28730140, 2017). "Another immune checkpoint involved in tumor immune-resistance is the interaction between programmed cell death-1 (PD-1) and programmed death-ligand 1 (PD-L1)." (PMID 28148257, 2017). "Tumor tissues from 76 Chinese DLBCL patients were immunostained for programmed cell death 1 (PD-1), PD-L1, and TP63 using the EnVision system." (PMID 28403071, 2017). "It is therefore possible that the impaired tumor clearance we observed with PD-L1+ tumors is due in part to generation of immunosuppressive Tregs, and Pdcd1 deletion in CD4+ T cells abrogates this re-programming and enhances tumor clearance." (PMID 28389661, 2017). "In sum, these results suggest that Pdcd1 disruption can rescue functional defects induced in CD8+ anti-CD19 4-1BBζ CAR T cells by PD-L1+ tumor cells." (PMID 28389661, 2017). "Pdcd1 disruption (ΔPD-1) rescued the defect in degranulation (CD107a expression) observed following stimulation of CD8+ CAR T cells with CD19+ PD-L1+ tumor cells, in contrast to control Cas9 nucleofected cells." (PMID 28389661, 2017). "Activation of the programmed cell death-1 (PD-1)/PD-L1 signaling pathway leads to an immunosuppressive tumor microenvironment, which results in immune evasion by tumor cells." (PMID 28938605, 2017). "Programmed cell death 1 is considered to be an exhaustion marker expressed on CD8+ T cells during chronic infection or tumor progression; however, PD-1 expression on CXCR5+CD8+ T cells during chronic HIV infection remains poorly defined." (PMID 29312314, 2017). "Combined, our results indicate that CRISPR-mediated targeted disruption of the Pdcd1 locus can enhance in vivo anti-tumor efficacy of human CAR T cells." (PMID 28389661, 2017). "The programmed cell death-1/programmed cell death-1 ligand (PD-1/PD-L1) pathway has shown to play a crucial role in tumour immune invasion." (PMID 28511705, 2017). "Programmed cell death-1 (PD-1) plays an important inhibitory role in anti-tumor responses, so it is considered as a powerful candidate gene for individual’s genetic susceptibility to cancer." (PMID 27031235, 2016). "The expression of the programmed cell death 1 (PD-1), a member of the B7 family of immune-regulatory cell-surface proteins, and its cognate ligand PD-L1, within the tumor microenvironment is a major resistance mechanism for escaping immune surveillance." (PMID 27227453, 2016). "An alternate mechanism of immune evasion that has gained recent attention is modulation of tumor immunity by the programmed cell death-1 (PD-L1/PD-1) immune checkpoint pathway." (PMID 27239288, 2016). "Programmed cell death 1(PD-1) was a co-inhibitory molecule receptor expressed by activated T cells, and its ligands PD-L1 was expressed on tumor cells as well as stromal cells." (PMID 27558285, 2016). "Both the microenvironment (65 %) and the tumor cells (22 and 5 %) showed expression of programmed cell death-1 (PD-1) and programmed cell death-ligand 1 (PDL-1) with the EBV-positive cases more often positive." (PMID 27766120, 2016). "Some studies concluded that PD-L1 expression is up regulated in solid tumors, where it can provide direct tumor protection and reduce activity of PDCD1 expressing, tumor-infiltrating effector CD4 and CD8 T cells." (PMID 26562534, 2015). "One of the most promising pathways for manipulation involves PD-L1, where its up-regulated expression in solid tumors provides direct tumor protection as well as reducing the activity of PDCD1 expressing tumor-infiltrating effector CD4 and CD8 T cells." (PMID 26562534, 2015). "Here, we propose that the abundant presence of tumour antigen as well as tight CLL-T cell interactions in lymphoid tissues induce expression of PDCD1 on T cells." (PMID 25940792, 2015).
tumor (continued). "Majority of the TIM-3+ tumor-infiltrating CD8+ T cells (>75%) also expressed PD-1 (Programmed cell death 1) on their surface." (PMID 26493689, 2015). "These recent findings strongly suggest a fundamental contribution of the PDCD1/CD274 pathway to CLL tumour escape strategies." (PMID 25940792, 2015). "The data showed that OT-1-Lag3−/−Pdcd1−/− tumor-bearing mice exhibited significantly improved survival compared with OT-1-WT or single knock out OT-1-Lag3−/− or OT-1-Pdcd1−/− mice (p = 0.0001, Log-rank test)." (PMID 26318293, 2015). "It plays an important role in negatively regulating both the expansion of activated primary T cells and the development of the memory T cell pool and, together with PDCD1, synergistically inhibits T cell functions to promote tumour immune escape." (PMID 25940792, 2015). "In fact, a combination of cyclophosphamide and PDCD1 antibody resulted in synergistic augmentation of anti-tumour response in a murine tumour vaccination study." (PMID 25940792, 2015). "First of all, this finding suggests that the PDCD1+ CTLs in these mice are indeed functionally exhausted and contain tumour-specific clones that can be reinvigorated by inhibiting PDCD1 ligation." (PMID 25940792, 2015). "IHC confirmed that PD-1 protein (PDCD-1) was heterogeneously expressed on tumor cells in both the D65140 PHT and its first-generation CX." (PMID 24278200, 2013). "Furthermore, conditional ZFP148 ablation in CD8+ T cells synergized with programmed cell death-1 blockade to improve tumor control in syngeneic mouse models." (PMID 41896465, 2026). "We subsequently assessed whether tumor communication is reduced after applying anti-programmed cell death 1 (PD-1) therapy." (PMID 39954673, 2025). "Humanized or fully human monoclonal antibodies specially designed to break cancer immune tolerance by restoring T cell recognition against tumor cells, ICIs dampen the cytotoxic T-lymphocyte-associated antigen 4 (CTLA-4) and the programmed cell death 1 (PD-1)/ligand (PD-L1) pathways." (PMID 40558275, 2025). "Moreover, the genes related to T cell activation, such as Pdcd1, Cxcr6, Gzma, Gzmb, and Prf1, also upregulated in the tumor of αmPD1-IL-2x and mAWT020 treated mice." (PMID 40046051, 2025). "Additionally, the exploration of PDCD1 gene knockout is aimed at potentially enhancing the anti-tumor responses of CAR-T cells." (PMID 40027883, 2025). "Several studies have highlighted that the expression of PDCD1 is not only regulated at the genetic level, but also through epigenetic mechanisms that may influence tumor behavior and prognosis." (PMID 40869918, 2025). "Furthermore, increased expression levels of CTLA4 and PDCD1 were also observed in tumor patients exhibiting hypoxia." (PMID 41419193, 2025). "Moreover, the FUSCC dataset (SRP157974) was used again to compare further characteristics, such as tumor stage, PDCD1, and CD274, in the FAM114A1-high/low patient groups." (PMID 41249116, 2025). "We discovered that chemotherapy reshaped the tumor immune microenvironment, evident through the reduction in human leukocyte antigen (HLA) diversity and the increase in PDCD1/CD274 in CD8_ANXA1, LAMP3+ dendritic cell (DC_LAMP3), and EREG+ monocytes (mono_EREG)." (PMID 40725006, 2025). "They showed that Tussilago farfara L. polysaccharides decreased the expression of programmed cell death-1 protein (PD-1) and the ligand of programmed cell death-1 protein (PD-L1) in peripheral blood and tumor tissue lymphocytes in vivo in C57BL/6 mice with Lewis LC." (PMID 40143000, 2025). "The markedly decreased Treg infiltration in murine ICC tumors after R428 treatment encouraged us to investigate whether combining R428 with anti–programmed cell death 1 (anti–PD-1) therapy could further inhibit tumor growth." (PMID 39774471, 2025).
tumor (continued). "Immune checkpoints contribute to the malignant progression of tumor by regulating tumor immune microenvironment and promote malignant behaviors such as tumor cell proliferation and metastasis, including programmed cell death 1 (PD-1), poliovirus receptor (PVR), SIRPA and other immune checkpoints." (PMID 41024301, 2025). "We investigated whether anti-MIF therapy could enhance the antitumor effects of the immune checkpoint inhibitor anti–programmed cell death 1 (anti–PD-1) in 2 murine tumor models." (PMID 41122966, 2025). "Interestingly, we identified distinct developmental trajectories for the two CD8+ Tex subsets (CD8Tex_PDCD1 and CD8Trm_LAG3), reminiscent of the exhaustion paths observed in tumor-infiltrating T cells." (PMID 40589761, 2025). "CD96, CTLA - 4, and PDCD1 are key proteins in tumor immune evasion." (PMID 40746529, 2025). "PDT can upregulate the programmed cell death 1 (PD-1)/PD-ligand 1(PD-L1) inhibitors, which will block the immunosuppressive signaling pathway and stimulate antitumor immune responses, leading to the killing of primary tumor tissue and blocking metastasis." (PMID 40243613, 2025). "While Tex cells were also abundant in the primary tumor tissue, the expression of exhaustion genes (PDCD1, CTLA4, and TIGIT) was notably higher in liver metastasis (LM) tissue, suggesting that T cell functional exhaustion in the metastatic microenvironment contributes to immune evasion." (PMID 40303346, 2025). "Notably, pharmacological inhibition of DUSP18 with lumacaftor, in combination with anti-PD-1 (programmed cell death 1 (PDCD1; also known as PD-1) immunotherapy, significantly suppressed tumor growth in vivo." (PMID 40659633, 2025). "Collectively, these results confirmed that the spatial and functional dependency between CAF-FAP and CD8_PDCD1 were broadly present in tumor stroma, extending our observations and clinical implications in human and mouse HCC to diverse origins of major cancer types." (PMID 39870619, 2025). "Since this breakthrough, several immune checkpoint inhibitors (ICIs), including programmed cell death 1 (PD-1) and its ligand programmed cell death ligand 1 (PD-L1), have been widely used for various tumors due to their sustained anti-tumor response and significant efficacy." (PMID 41463240, 2025). "A strong correlation with CST7 is maintained after adjusting for tumor purity (PDCD1, TIGIT)." (PMID 41229419, 2025). "Additional examination revealed that while circGRAMD4 siRNA and anti-PDCD1 single treatment both hindered tumor progression, the combination of si-circGRAMD4 and PDCD1 inhibition demonstrated a more pronounced effect in reducing tumor burden than either si-circGRAMD4 or anti-PDCD1 alone." (PMID 40373256, 2025). "Meanwhile, IFN-γ exerts protumoral functions by inducing immune checkpoint receptors, including programmed cell death 1 and indoleamine 2,3-deoxygenase in tumor cells, enhancing the metastatic ability of tumor cells while suppressing the migration of cytotoxic T cells." (PMID 40563696, 2025). "Also, CAR-NK expresses a lower level of programmed cell death-1 (PD-1) than CAR-T which makes them more potent against tumor cells." (PMID 40007761, 2024). "Similarly, the co-culturing of UPP1-overexpressing tumor cells with CD8 + T cells facilitated the transformation of CD8 + T cells towards a LAG3 + PDCD1+ exhausted T cell phenotype." (PMID 38331898, 2024). "High tumour mutation burden (TMB) has been shown to be a biomarker for immunotherapeutic response for treatments that inhibit programmed cell death 1/programmed death‐ligand 1 (PD‐1/PD‐L1) ligation in multiple tumours, thereby improving the survival of cancer patients." (PMID 38303608, 2024). "Similarly, in KIRP SIGLEC12 positive tumours, a weak positive correlation in PDCD1 (Fig. 4C1), CD274 (Fig. 6C2), CTLA4 (Fig. 6C3), IL-2 (Fig. 6C4) was observed." (PMID 38268823, 2024).
tumor (continued). "It simultaneously blocks CTLA-4 with CD80/85 and PD-L1 with programmed cell death-1 (PD-1) to inhibit immunosuppressive effects, which restores T-cell effector immune response to tumor and deletes Treg cells (suppress tumor immunity) in tumor microenvironment." (PMID 38310192, 2024). "Specifically, the immune checkpoints mediated by cytotoxic T-lymphocyte associated antigen-4 (CTLA-4), programmed cell death-1 (PD1), and programmed cell death ligand 1 (PD-L1) inhibit T-cell activation through their interaction with antigen-presenting cells or tumor cells." (PMID 39590149, 2024). "DSP proteomics and 10× Genomics Visium transcriptomics analyses revealed that a negative correlation (Spearman correlation analysis: r = –.886; p = .033) between the expression levels of CD8 and the expression trend of programmed cell death 1(PD‐L1) on tumour endothelial cells." (PMID 38318637, 2024). "Our findings indicated that immune checkpoints (PDCD1, ENTPD1 and TIGIT), the T-cell exhaustion state-associated transcription factor TOX, and the gene DDX58 (transcriptional protein RIG-I) are co-expressed in tumour-infiltrating CD8+ T cells (Fig. EV1A–D)." (PMID 39322862, 2024). "Tumor-infiltrating PDCD1+ and LAG3+ cells expressed CBLB, while a minor proportion expressed CBLC." (PMID 39030301, 2024). "Programmed cell death ligand 1 (PD-L1), expressed on many tumor cells, binds to programmed cell death 1 (PD-1) on T cells, B cells, NK cells, and myeloid derived suppressor cells (MDSCs) to drive an inhibitory response that suppresses T cell activity and fosters self-antigen tolerance." (PMID 38741774, 2024). "Furthermore, the combination of intraperitoneal OBP-702 with anti-programmed cell death-1 antibody enhanced anti-tumor immunity and prolonged the survival of mice bearing PM." (PMID 38745748, 2024). "The Adgrg1, Pdcd1, Osgin1, Lag3, and Chn2 were predominantly expressed in tumor-reactive T cells." (PMID 39243082, 2024). "Furthermore, among genes expressed at the 2 h post first dose of DSP-0509, Pdcd1 was found to predict complete tumor elimination with the highest predictive performance." (PMID 39054418, 2024). "Therefore, dMMR/MSI-H tumours are considered to be highly immunogenic, rendering them more sensitive to programmed cell death 1 (PD-1) and programmed cell death ligand 1 (PD-L1) inhibitors." (PMID 36870947, 2023). "As an important immune checkpoint axis, the Programmed Cell Death-1/ Programmed Death-ligand 1 (PD-1 / PD-L1) axis was first reported in autoimmune-induced inflammation, but now this axis was more famous for its role in suppressing anti-tumor immunity." (PMID 36698098, 2023). "Indeed, knockout or small hairpin RNA (shRNA)-mediated knockdown of PDCD1 enhanced the anti-tumor efficacy of C-type lectin-like molecule-1 (CLL-1)-, mesothelin-, epidermal growth factor receptor (EGFR)-, CD19-, and Glypican-3 (GPC3)- CAR-Ts." (PMID 37046597, 2023). "Importantly, infiltrating immune cells in the tumor overexpress PDCD1 as a strategy to evade immune responses." (PMID 37016451, 2023). "In a 4T1 tumor treated with cyclophosphamide, the single cell expression of Cd274 was found to increase both in myeloid- and lymphoid-infiltrated cells, independently of its receptor Pdcd1." (PMID 38201582, 2023). "Thus, the binding of PDCD1 to its ligands downregulates Teff cell activity and promotes tumor escape." (PMID 37215135, 2023). "CTLA-4 and PDCD1 blockade could induce tumor immunity by improving effector T cell activity or consuming Treg." (PMID 36900015, 2023). "The therapeutic mechanism of ICIs is based on targeting certain immunoregulatory signaling molecules, including cytotoxic T-lymphocyte antigen 4 (CTLA-4), programmed cell death 1 (PD-1), and its ligand 1 (PD-L1), which activate T cells and inhibit the growth of tumor cells." (PMID 37305530, 2023).